TLR4 (toll like receptor 4)
Diseases named in the same sentence as TLR4 in open-access papers (continued):
Sharing a sentence is not in itself a finding about the gene and the disease.
Alzheimer disease (continued). "Some observations suggest that the imbalance between TREM2 and TLR4 (toll-like receptor 4) signaling in favor of TLR4 may contribute to the development of Alzheimer’s disease." (PMID 37108808, 2023). "Experimental animal models of Alzheimer’s disease revealed that the production of NOD-like receptor pyrin domain containing 3 (NLRP3) via Toll-like receptor 4 (TLR4) and the activation of the NLRP3 inflammasome via P2X7 purine receptor are essential for induction of neural inflammation." (PMID 38983051, 2023). "TLR4 and inflammasomes were cross-talked in other disease models, e.g., Alzheimer’s disease." (PMID 36986437, 2023). "Moreover, in molecular docking, the tested compounds have been shown to bind to the TLR4/MD-2 complex, which plays an important role in Alzheimer's disease." (PMID 36129673, 2022). "Here, we reported a deep analysis (in white and gray matter in the frontal cortex and cerebellum) in a single case, using a matched control subject and a positive control in which TLR4-induced neuroinflammation has been extensively reported, as in an aged brain with Alzheimer’s disease." (PMID 36225571, 2022). "Most overrepresented molecular function annotations were amyloid beta binding activity—an activity presented by proteins such as ITGAM (also named CD11b) and TLR4 —as well as cytokine receptor binding activity, further linking the amyloid peptide to the innate immune response in Alzheimer's disease." (PMID 34335238, 2021). "Indeed, increased TLR4 expression has been identified in the brains of patients with Alzheimer’s disease, while persistent TLR4 stimulation in rodent models of Alzheimer’s disease exacerbates disease burden." (PMID 34838047, 2021). "The protein encoded by Jun, jun proto-oncogene, a transcription factor involved in JNK-mediated transcriptional changes, has been identified as a crucial part in the mediation of TLR4-dependent neuroinflammation and in the ocular degeneration occurring in an Alzheimer’s disease mouse model." (PMID 33981252, 2021). "However, in other diseases such as Alzheimer’s disease, IL-10 production occurs through a mechanism involving TLR4." (PMID 32532251, 2020). "This indicates that TLR4 signaling may play a role in Alzheimer’s disease (AD) pathogenesis, possibly being activated by membrane-associated oxidative stress." (PMID 31212769, 2019). "However, TLR4 activation in microglia with endogenous ligands, such as amyloid β were shown to be a critical mechanism also in the development of Alzheimer disease." (PMID 26109901, 2014). "In Alzheimer’s disease, TLR4 may exhibit beneficial or deleterious effects, depending on the conditions of its activation." (PMID 24244457, 2013). "In addition, TLR4-deficient mice displayed increases in diffuse amyloid beta-protein and its deposits compared with WT mice, suggesting that TLR4 signaling might be involved in Alzheimer's disease progression and could be a new therapeutic target for Alzheimer's disease." (PMID 23441224, 2013). "It is increasingly thought that Parkinson's disease, Alzheimer's disease, spinal cord injury, seizures, and excitotoxicity may involve a microglial response that is regulated by TLR4 signaling." (PMID 19489097, 2009). "In the Alzheimer’s disease (AD) model, LYN directly binds to TLR4 and regulates the inflammatory and phagocytic functions of microglia." (PMID 40692778, 2025). "This study aimed to investigate the expression and role of Signaling Lymphocytic Activation Molecule Family Member 8 (SLAMF8) in Alzheimer’s disease (AD), particularly its interaction with NINJ2 in the TLR4/NF-κB signaling pathway." (PMID 40394132, 2025). "Elevated TLR-4 and TLR-2 mRNA and protein levels were observed in peripheral blood mononuclear cells (PBMCs) for late-onset Alzheimer’s Disease (LOAD) patients." (PMID 39334369, 2024). "In both human brains and animal models of Alzheimer's disease, there is an upregulation of TLR2, TLR4, and CD14 expression." (PMID 38698886, 2024).
Alzheimer disease (continued). "* Alzheimer's disease (AD): increased expression of TLR2, TLR4, and CD14 has been observed in human brains and animal models of AD." (PMID 38698886, 2024). "The binding affinity at the TLR4/MD-2 complex binding site of TP4 and TP8 compounds is similar to that of the drug donepezil used in Alzheimer's disease." (PMID 36129673, 2022). "Systemic administration of a weak TLR4 agonist monophosphoryl lipid A (MPLA) led to a substantial reduction in amyloid β load in the brain and to a significant improvement in Alzheimer’s-disease-related pathology in mice." (PMID 36678520, 2022). "Upregulation of TLRs expression was observed in a variety of chronic neurodegenerative diseases, such as Alzheimer’s disease (TLR2 and TLR4), multiple sclerosis (TLR 1-8), and Parkinson’s disease (TLR2 and TLR5)." (PMID 35740099, 2022). "This study is focused on the potential roles of various TLRs in various neurodegenerative diseases such as Parkinson’s disease (PD) and Alzheimer’s disease (AD), namely TLR2, TLR3, TLR4, TLR7, and TLR9 in AD and PD in human beings and a mouse model." (PMID 34827372, 2021). "Recently, TLR4 and TLR2 have been shown to play a significant role in neuroinflammation occurring during Alzheimer's disease." (PMID 28790798, 2017). "In addition, recent studies indicate that TLR4 expression is upregulated with normal aging, suggesting an altered regulation of the innate immune response in aging that may be relevant in different neurodegenerative disorders such as Alzheimer’s disease (AD)." (PMID 28143556, 2017). "It is shown that fibrillar amyloid β (Aβ) can directly interact with Toll-like receptor 2 (TLR2), TLR4, and CD14 to induce microglial Aβ phagocytosis at the initial stages and neuroinflammatory responses at the late stages of Alzheimer's disease." (PMID 25563673, 2014). "Toll like receptor 4 (TLR4) has been related to inflammation and beta-amyloid deposition in Alzheimer's disease (AD) brain." (PMID 23272070, 2012). "The activation of microglia with peptidoglycan as TLR2 ligand, LPS as agonist for TLR4, or TLR9 ligand CpG, markedly boosted the ingestion of Alzheimer's disease neurotoxic Amyloid β (Aβ) protein in vitro." (PMID 20706642, 2010). "For example, heterophyllin B exhibits neuroprotective effects in Alzheimer’s disease models but lacks direct evidence of modulating the BACE1 enzyme; polysaccharides show TLR4-mediated immune regulation, yet their synergistic interactions with cyclic peptides remain unstudied." (PMID 40942180, 2025). "While TLR2, TLR4, TLR5 and TLR10 might be involved in the pathogenesis of systemic sclerosis, TLR activation can have both destructive and protective effects on Alzheimer ́s disease (AD)." (PMID 33499143, 2021). "In Alzheimer’s disease (AD), soluble amyloid-β oligomers and fibrils interact with cell-surface receptors (e.g., integrin, CD14, and the Toll-like receptors TLR2 and TLR4) in microglial cells, and these interactions can also trigger a neuroinflammatory response." (PMID 30319390, 2018). "On the other hand, highly hydrophobic non-glycolipid TLR4 antagonists, such as (+)-naltrexone, are better suited to target CNS diseases such as neuroinflammation, neuropathic pain, and neurodegenerative diseases including Alzheimer's disease (AD)." (PMID 32765484, 2020).
inflammatory bowel disease (115 papers, 2010 to 2026). A spectrum of small and large bowel inflammatory diseases of unknown etiology. "A meta-analysis provided evidence that the TLR4 Asp299Gly polymorphism is associated with an increased risk of both Crohn’s disease and overall inflammatory bowel disease." (PMID 41583491, 2025). "Increased epithelial TLR4 signaling is also associated with inflammatory bowel disease (IBD) and colorectal tumorigenesis." (PMID 37576399, 2023). "It has been suggested that unusual microbiota induce TLR4 signaling, leading to certain diseases, inflammatory bowel disease (IBD), colitis-associated cancer, diabetes, Alzheimer’s disease, and Parkinson’s disease." (PMID 33810392, 2021). "TLR4 is implicated in many other inflammatory diseases such as psoriasis, inflammatory bowel disease, and SLE." (PMID 35126351, 2021). "NF-κB activation, a downstream pathway of TLR-4, is a hallmark for inflammation, contributing to chronic diseases such as inflammatory bowel disease, systemic inflammatory response syndrome, and chronic inflammatory demyelinating polyradiculoneuritis." (PMID 26869924, 2016). "Elevated toll-like receptor 4 (TLR4) expression is associated with a decreased mucus layer, inflammatory bowel disease and CRC progression." (PMID 26894861, 2016). "Increased frequency of TLR4(Asp299Gly) occurred in Crohn’s disease and ulcerative colitis, indicating a potential role for deficient host-bacterial interactions underlying inflammatory bowel disease." (PMID 26361369, 2015). "TLR-4 naturally binds to bacterial LPS and is linked to gut inflammation and inflammatory bowel diseases like ulcerative colitis." (PMID 24551212, 2014). "TLR4 A1571T and TLR4 G1807A genotype association with inflammatory bowel disease in German shepherd dogs." (PMID 21203467, 2010). "TLR4 has been implicated in several similar diseases, particularly inflammatory bowel disease." (PMID 40637163, 2025). "Interestingly, increased genes associated with innate immune cell activation after TLR4 stimulation overlapped with increased immune activation processes in brains from inflammatory bowel disease (IBD)." (PMID 35082275, 2022). "For example, toll-like receptor 4 (TLR-4) was reported to be overexpressed in cases of inflammatory bowel disease and was concomitantly associated with increased tissue levels of nuclear factor kappa B (NF-κB), which is considered the key mediator of the inflammatory process." (PMID 35631426, 2022). "Interestingly, upregulation of TLR4 is associated with inflammatory bowel diseases like ulcerative colitis." (PMID 32314963, 2020). "Furthermore, antibodies against CL have been identified in patients with lupus, inflammatory bowel disease, and Antiphospholipid Syndrome, diseases that are thought to be linked to TLR4." (PMID 31062071, 2019). "Some variants of the TLR4 genes are considered to be risk factors of inflammatory bowel disease (IBD) and PD." (PMID 37305758, 2023). "For example, TLR4 signaling activation triggers a cascade of events leading to inflammatory response of innate immune cells via NF-B activation as well as activated T cell responses, which is considered as the major immunological cause in the onset of inflammatory bowel disease." (PMID 33799689, 2021). "On the other hand, increased expression of TLR4 has been linked to inflammatory bowel disease (IBD) in dogs." (PMID 25591990, 2015). "It is worth noting that PRSS8 inhibits TLR4-mediated inflammation in human and mouse models of inflammatory bowel disease, thereby implicating its plausible relevance to TLR4-mediated inflammation pathways in the context of MG." (PMID 38521921, 2024). "Moreover, the functional association of TLR4 is well established for other pro-inflammatory clinical abnormalities such as inflammatory bowel disease (IBD) and necrotizing enterocolitis (NEC)." (PMID 37153546, 2023).
inflammatory bowel disease (continued). "As an important receptor for innate immune recognition, TLR4 is indispensable in homeostasis, intestinal inflammation, and inflammatory bowel disease in vivo." (PMID 38152693, 2023). "Studies have shown that by downregulating the expression of TLR4 and NF-κB, the body’s inflammatory response can be reduced, and it has a therapeutic effect on inflammatory bowel disease in the mouse model by inhibiting the over-activation of TLR4/NF-κB." (PMID 36164339, 2022). "Previous studies have confirmed that TLR4 plays an important role in a broad range of intestinal diseases such as inflammatory bowel disease and NEC." (PMID 36211338, 2022). "A recent report showed a new soluble protein from LGG, HM0539, suppress inflammation by inhibiting the TLR4/MyD88/NF-κB signaling, which is considered as a potential therapeutic option for inflammatory bowel disease (IBD)." (PMID 36569920, 2022). "It has been reported that the levels of TLR4 are significantly elevated in intestinal epithelial cells and macrophages in active inflammatory bowel disease." (PMID 33499808, 2021). "A previous report showed increased expression levels of TLR2 and TLR4 in patients with inflammatory bowel diseases (IBDs), which are chronic inflammatory syndromes of the gastrointestinal tract." (PMID 30823938, 2019). "TLR-4 has been reported to be expressed at low levels in basal conditions in vivo but it is upregulated in inflammatory bowel disease." (PMID 29970837, 2018). "Several studies have demonstrated that TLR4 expression is known to be low in the normal colon but increased in inflammatory bowel disease (ulcerative colitis and Crohn's disease)." (PMID 28408791, 2017). "For genes encoding transcellular transporters, we found a very significant increase in the expression levels of ion transport gene Clca4 (chloride channel calcium activated 4), a biomarker of inflammatory bowel disease, in the colonic ECs of villin-TLR4 mice." (PMID 26755160, 2016). "There is evidence that TLR4 plays an important role in intestinal homeostasis and protection from injury to intestinal mucosa in inflammatory bowel disease." (PMID 25793763, 2015). "In conclusion, enhanced TLR-2 and TLR-4 expression by crypt epithelial cells in active inflammatory bowel disease likely reflects greater ability to respond to microbial products." (PMID 24828022, 2014). "Defect or damage in the TLR2 and TLR4 pathways can lead to sustained inflammation, characteristic of inflammatory bowel disease (IBD)." (PMID 25415606, 2014). "We and others have shown that IEC of the mature, healthy small and large intestine express low levels of TLR4 and MD-2 and respond poorly to LPS, but TLR4 and MD-2 are abnormally upregulated in inflammatory bowel disease." (PMID 20976181, 2010). "The TLR4-NF-κB signaling axis may represent a critical mechanistic link between Inflammatory bowel disease (IBD) and CRC, suggesting novel therapeutic and preventive strategies for IBD and CRC." (PMID 41048488, 2025). "After HKC treatment, Tlr4 was downregulated and enriched in the inflammatory bowel disease pathway." (PMID 39529886, 2024). "Studies have demonstrated that the down-regulation of TLR4 and NF-κB expression mitigates the organism’s inflammatory response, showing therapeutic efficacy in a murine model of inflammatory bowel disease through the inhibition of the TLR4/NF-κB signaling pathway." (PMID 39133675, 2024). "Indeed, human IECs constitutively express TLR3, TLR5, TLR9, NOD1, NOD2 and low levels of TLR2 and TLR4, where TLR4 is increased in inflammatory bowel disease (IBD) IECSs and intestinal macrophages." (PMID 36296363, 2022). "The activation of the TLR4/NF-κB signaling pathway could modulate NLRP3 inflammasome activation in inflammatory bowel disease and induce GSDMD-mediated pyroptosis in tubular cells in diabetic kidney disease." (PMID 34646128, 2021).
inflammatory bowel disease (continued). "Several researches have showed that various TCM formulations and compounds could alleviate inflammatory bowel diseases through TLR4/MyD88 pathway, nonetheless whether modified PD takes effect through via this signaling still needs further investigation." (PMID 32517784, 2020). "Furthermore, TLR4 possibly activate down-stream JAK/STAT pathway to secrete IL-17A in inflammatory bowel disease, which suppressed WNT pathway through stimulating DKK1 in intestinal stem cells." (PMID 29228588, 2017). "Increased epithelial TLR4 expression is observed in patients with inflammatory bowel disease." (PMID 26755160, 2016). "In addition, TLR-4 has been found to be more highly expressed in intestinal epithelial cells and lamina propria immune cells of inflammatory bowel disease (IBD) patients." (PMID 24551212, 2014). "For example, acetate and butyrate have been shown to downregulate TLR4-mediated inflammatory responses, a key pathway involved in diseases such as inflammatory bowel disease (IBD)." (PMID 41230178, 2025). "Several SNPs were identified in the TLR-4 and TLR-5 genes in the German Shepherd breed that are associated with inflammatory bowel disease (IBD)." (PMID 40725420, 2025). "On the other hand, in patients with inflammatory bowel disease (IBD), an increase in the expression of mucosa-located TLR4 has been reported." (PMID 38674014, 2024). "However, in inflammatory bowel disease, TLR4-NF-κB overexpression and overactive TLR4-NF-κB signal transduction may damage intestinal mucosal homeostasis, leading to tissue damage and inflammation." (PMID 37125181, 2023). "There are many toll-like receptor subtypes, and TLR-4 is one of these subtypes, which plays a major role in inflammatory bowel diseases (IBD)." (PMID 37895902, 2023). "Evidence indicated that TLR4 is highly upregulated in Inflammatory Bowel Disease (IBD) and DSS-induced UC in mice." (PMID 36193153, 2022). "Increased TLR4 and TLR2 expression is also associated with both Inflammatory Bowel Disease (IBD) and CeD, implicating dysbiosis in disease pathogenesis." (PMID 31590358, 2019). "In recent years, the role of TLR4 has become a hot topic again in various pathogenesis of intestinal diseases, such as inflammatory bowel disease (IBD)." (PMID 31671112, 2019). "Colonic IECs from patients with inflammatory bowel disease (IBD) have higher expression levels of TLR4 in particular, as well as lower levels of TLR2 and TLR5." (PMID 29438282, 2018). "The associations between toll-like receptor 2 (TLR2) and toll-like receptor 4(TLR4) polymorphisms and inflammatory bowel disease (IBD) susceptibility remain controversial." (PMID 26023918, 2015). "In inflammatory bowel disease (IBD), the expression of TLR4 in intestinal epithelium is highly increased." (PMID 24780093, 2014). "Although normal human ileal epithelium barely expresses TLR4, its expression is up-regulated in inflammatory bowel disease (IBD)." (PMID 25071777, 2014). "Two disease-related pathways — inflammatory bowel disease (cfa05321; GATA3, TLR4) and cancer pathways (cfa05222; COL4A1, E2F3, RARB) — were also enriched." (PMID 40764990, 2025). "For example, LPS, adhesins, and other virulence factors in the periodontal bacterium Fusobacterium nucleatum-derived EVs interact with Toll-like receptor (TLR)-4 and induce the expression of IL-8 and TNF-α in patients with inflammatory bowel disease (IBD)." (PMID 39698538, 2024). "In inflammatory bowel disease (IBD), TLR-4 in intestine induces a Th1 inflammatory response, producing the inflammatory cytokines IFN-γ and tumor necrosis factor (TNF), and then upregulating TLR-4, forming an “autocrine loop”." (PMID 38012694, 2023). "These probiotics have been reported to have good therapeutic potential in treating diarrhea, inflammatory bowel disease, and acute pancreatitis, and the primary mechanism might be through the modulation of the nuclear factor-kappa B (NF-κB) signaling pathway mediated by toll-like receptor 4 (TLR4)." (PMID 34712822, 2021).